PCMTD2 (protein-L-isoaspartate (D-aspartate) O-methyltransferase domain containing 2)
Description:
May act as a substrate recognition component of an ECS (Elongin BC-CUL5-SOCS-box protein) E3 ubiquitin ligase complex which mediates the ubiquitination and subsequent proteasomal degradation of target proteins. May bind to the methyltransferase cofactor S-adenosylmethionine (AdoMet) via the N-terminal AdoMet binding motif, but probably does not display methyltransferase activity.
Synonyms: C20orf36; FLJ10883
Tractability: PROTAC: ubiquitination databases record sites on it; its protein half-life has been measured.
Gene: Protein-coding gene on chromosome 20 (64,254,921 to 64,304,820, forward strand). Ensembl gene ENSG00000203880.
Subcellular location: Cytoplasm
Subcellular location (Human Protein Atlas): Mitochondria; Nucleoplasm
Gene Ontology:
Molecular function: protein binding; protein-L-isoaspartate (D-aspartate) O-methyltransferase activity
Cellular component: cytoplasm
Genetic constraint (gnomAD): Loss-of-function variants: 12 observed, 22.49 expected, observed/expected ratio (o/e) 0.53, 90% interval 0.34 to 0.87. The upper end of that interval is the gene's LOEUF score, 0.87, which puts it in group 3 of 6, group 1 being the genes least tolerant of losing a copy. Missense variants: 271 observed, 349.09 expected, observed/expected ratio (o/e) 0.78, 90% interval 0.7 to 0.86. Synonymous variants: 128 observed, 127.41 expected, observed/expected ratio (o/e) 1, 90% interval 0.87 to 1.16.
Homologues: Orthologues: chimpanzee PCMTD2 (100% identical), macaque PCMTD2 (99% identical), dog PCMTD2 (96% identical), pig PCMTD2 (96% identical), rabbit PCMTD2 (94% identical), mouse Pcmtd2 (91% identical), tropical clawed frog pcmtd2 (76% identical), zebrafish pcmtd2a (70% identical), zebrafish PCMTD2 (68% identical), rat Pcmtd2 (56% identical), Caenorhabditis elegans R119.5 (25% identical). Paralogues in human: PCMTD1 (66% identical), PCMT1 (15% identical).
Diseases named in the same sentence as PCMTD2 in open-access papers:
PCMTD2 is named in the same sentence as 4 diseases in open-access papers, as found by Europe PMC text mining. Sharing a sentence is not in itself a finding about the gene and the disease. The quoted sentences say what the papers report.
Intellectual disability (1 paper, 2022). "A case report also shows that the loss of the PCMTD2 gene seems to be responsible for severe intellectual disability." (PMID 36186431, 2022).
schizophrenia (1 paper, 2022). A major psychotic disorder characterized by abnormalities in the perception or expression of reality. "As we can see from above, both DGKB and PCMTD2 are closely related to the brain and have the possibility to be associated with schizophrenia." (PMID 36186431, 2022). "A previous study has shown that PCMTD2 is one of the neurodevelopmental disorders associated genes linked across more than one disorder, including schizophrenia." (PMID 36186431, 2022). "There are some clues that suggest PCMTD2 might be related to schizophrenia." (PMID 36186431, 2022).
cancer (3 papers, 2022 to 2025). A tumor composed of atypical neoplastic, often pleomorphic cells that invade other tissues. "A genome-wide association study of 2057 European patients with advanced cancer receiving opioid treatment identified PCMTD2 and OPRL1 on chromosome 20 as associated with variations in the regulation of cancer pain intensity." (PMID 40579593, 2025). "TK1 has long been used as a diagnostic and prognostic marker in AML, and PCMTD2 and LRRC40 have been used as diagnostic or prognostic markers in other types of cancer." (PMID 35656299, 2022).
PCMTD2 also shares sentences with these, for which no sentence is quoted: neurodevelopmental disorder (1 paper).